NPM1 (nucleophosmin 1)
Description:
Binds ribosome presumably to drive ribosome nuclear export. Associated with nucleolar ribonucleoprotein structures and bind single-stranded nucleic acids. Acts as a chaperonin for the core histones H3, H2B and H4. Stimulates APEX1 endonuclease activity on apurinic/apyrimidinic (AP) double-stranded DNA but inhibits APEX1 endonuclease activity on AP single-stranded RNA. May exert a control of APEX1 endonuclease activity within nucleoli devoted to repair AP on rDNA and the removal of oxidized rRNA molecules. In concert with BRCA2, regulates centrosome duplication. Regulates centriole duplication: phosphorylation by PLK2 is able to trigger centriole replication. Negatively regulates the activation of EIF2AK2/PKR and suppresses apoptosis through inhibition of EIF2AK2/PKR autophosphorylation. Antagonizes the inhibitory effect of ATF5 on cell proliferation and relieves ATF5-induced G2/M blockade. In complex with MYC enhances the transcription of MYC target genes. May act as chaperonin or cotransporter in the nucleolar localization of transcription termination factor TTF1 (By similarity).
Synonyms: NPM; B23
Tractability: Small molecule: an approved drug acts on it; a structure with a bound ligand is known; a high-quality ligand is known; it belongs to a druggable protein family. PROTAC: UniProt records ubiquitination sites on it; ubiquitination databases record sites on it; its protein half-life has been measured; a small molecule that binds it is known.
Target class: Other nuclear protein
Gene: Protein-coding gene on chromosome 5 (171,387,086 to 171,411,810, forward strand). Ensembl gene ENSG00000181163.
Subcellular location: Nucleus, nucleolus; Nucleus, nucleoplasm; Cytoplasm, cytoskeleton, microtubule organizing center, centrosome
Subcellular location (Human Protein Atlas): Nucleoli rim; Nucleoplasm
Pathways (Reactome):
Disease: ALK mutants bind TKIs; Nuclear events stimulated by ALK signaling in cancer; Nuclear import of Rev protein; SARS-CoV-1-host interactions; Signaling by ALK fusions and activated point mutants
Gene expression (Transcription): TFAP2A acts as a transcriptional repressor during retinoic acid induced cell differentiation
Cell Cycle: Deposition of new CENPA-containing nucleosomes at the centromere
Immune System: PKR-mediated signaling
Metabolism of proteins: SUMOylation of transcription cofactors
Gene Ontology:
Molecular function: core promoter sequence-specific DNA binding; DNA-binding transcription factor binding; histone binding; molecular adaptor activity; NF-kappaB binding; protein binding; protein homodimerization activity; protein kinase binding; protein kinase inhibitor activity; ribosomal large subunit binding; ribosomal small subunit binding; RNA binding; rRNA binding; Tat protein binding; transcription coactivator activity; chromatin binding; identical protein binding; nucleic acid binding
Biological process: canonical NF-kappaB signal transduction; cellular response to UV; cellular senescence; centrosome cycle; DNA repair; intracellular protein localization; macrophage differentiation; negative regulation of apoptotic process; negative regulation of cell population proliferation; negative regulation of centrosome duplication; nucleocytoplasmic transport; nucleosome assembly; positive regulation of cell cycle G2/M phase transition; positive regulation of cell population proliferation; positive regulation of cytoplasmic translation; positive regulation of DNA-templated transcription; positive regulation of transcription by RNA polymerase II; protein import into nucleus; regulation of centriole replication; regulation of mRNA stability involved in cellular response to UV; chromatin remodeling; intracellular protein transport; regulation of centrosome duplication; ribosomal large subunit biogenesis; ribosomal large subunit export from nucleus; and 7 more
Cellular component: centrosome; cytoplasm; focal adhesion; membrane; nucleolus; nucleoplasm; nucleus; protein-containing complex; protein-DNA complex; ribonucleoprotein complex; spindle pole centrosome; cytosol; granular component; large ribosomal subunit; nuclear speck; small ribosomal subunit
Genetic constraint (gnomAD): Loss-of-function variants: 1 observed, 15.16 expected, observed/expected ratio (o/e) 0.066, 90% interval 0.022 to 0.31. The upper end of that interval is the gene's LOEUF score, 0.31, which puts it in group 1 of 6, group 1 being the genes least tolerant of losing a copy. Missense variants: 108 observed, 155.95 expected, observed/expected ratio (o/e) 0.69, 90% interval 0.59 to 0.81. Synonymous variants: 68 observed, 52.2 expected, observed/expected ratio (o/e) 1.3, 90% interval 1.07 to 1.59.
Gene-disease validity (ClinGen):
ClinGen rates the evidence that NPM1 causes each of these diseases.
bone marrow failure syndrome (autosomal dominant): Limited.
Cancer hallmarks: escaping programmed cell death (promotes); proliferative signalling (promotes); invasion and metastasis (promotes); change of cellular energetics (promotes); suppression of growth (promotes); genome instability and mutations (suppresses)
Homologues: Orthologues: chimpanzee NPM1 (100% identical), macaque NPM1 (99% identical), pig NPM1 (98% identical), zebrafish npm1a (48% identical), Drosophila melanogaster Nph (18% identical), Drosophila melanogaster Nlp (16% identical). Paralogues in human: NPM2 (23% identical), NPM3 (22% identical).
Diseases named in the same sentence as NPM1 in open-access papers:
NPM1 is named in the same sentence as 216 diseases in open-access papers, as found by Europe PMC text mining. Sharing a sentence is not in itself a finding about the gene and the disease. The quoted sentences say what the papers report.
acute myeloid leukemia (373 papers, 2006 to 2026). Acute myeloid leukemia (AML) is a group of neoplasms arising from precursor cells committed to the myeloid cell-line differentiation. "Among NPM1-mutated acute myeloid leukemia (AML) (NPM1 mut), a distinct subtype has been described with an immunophenotypic profile resembling acute promyelocytic leukemia (APL-like)." (PMID 42007444, 2026). "Mutations in NPM1, such as those found in acute myeloid leukaemia (AML), lead to its mislocalization, disrupting its ability to regulate apoptosis ⁠⁠." (PMID 40068812, 2025). "Mutations in NPM1 are among the most common genetic alterations in adult patients with acute myeloid leukemia affecting around 30% of them." (PMID 40629154, 2025). "Characteristic C-terminal mutation of the NPM1 gene resulting in the aberrant localization of mutated NPM protein (NPMmut) to the cytoplasm appears in about 50% of acute myeloid leukemia (AML) with normal karyotype." (PMID 40334261, 2025). "Label-free holo-tomographic flow cytometry enables 3D analysis of nuclei in suspended cells of acute myeloid leukemia, revealing a correlation between NPM1-mutations and cup-like morphology, potentially improving diagnostics with virtual reality integration." (PMID 40603297, 2025). "Acute myeloid leukemia (AML) harboring nucleophosmin 1 (NPM1) mutations represents a biologically and clinically distinct subset, occurring in approximately one-third of adult patients and in over half of those with a normal karyotype." (PMID 41374935, 2025). "Acute myeloid leukemia (AML) is profoundly affected by mutations in the NPM1, particularly in its mutant form known as NPMc+." (PMID 39757214, 2025). "Cup-like nuclear morphological alterations in acute myeloid leukemia (AML) blasts have been widely correlated with Nucleophosmin 1 (NPM1) mutations." (PMID 40603297, 2025). "We report a case of acute myeloid leukemia (AML) with mutated NPM1, presenting with severe hypereosinophilia, organ involvement, and a low blast count." (PMID 40567444, 2025). "Quantitative assessment of nucleophosmin 1 (NPM1) mutation status is integral to evaluating measurable residual disease (MRD) in NPM1-mutated acute myeloid leukemia (AML) patients." (PMID 39063154, 2024). "Mutations in NPM1 occur in approximately one-third of patients with acute myeloid leukemia and are clinically associated with leukocytosis, a high percentage of blasts, and extramedullary involvement." (PMID 39120297, 2024). "Acute myeloid leukemia with NPM1, IDH2, and SETD2 mutations can mimic acute promyelocytic leukemia (APL) and poses a challenge for the early and accurate differentiation and diagnosis of APL with PML::RARA." (PMID 39432585, 2024). "Nucleophosmin (NPM1) is a nucleolar protein and one of the most frequently mutated genes in acute myeloid leukemia (AML)." (PMID 39443736, 2024). "Background and Objectives: With the advent of novel therapies for nucleophosmin gene (NPM1)-mutated acute myeloid leukemia (AML), there is a growing need for the reliable prediction of NPM1 mutations." (PMID 39336484, 2024). "Nucleophosmin 1 (NPM1) is mutated in approximately 30% of adult de novo acute myeloid leukemia (AML) cases." (PMID 38633114, 2024). "Nucleophosmin 1 (NPM1) gene‐mutated acute myeloid leukemia (NPM1mut AML) is classified as a subtype with a favorable prognosis." (PMID 39126219, 2024). "Acute myeloid leukemia (AML) with mutation of NPM1 (NPM1m AML) is a distinct entity, accounting for around 30% of AML cases, with peak incidence in middle age." (PMID 39457595, 2024). "Genetic abnormalities caused by NPM1 mutations often occur in human acute myeloid leukemia, which accounts for about one‐third of all cases." (PMID 36875159, 2023).
acute myeloid leukemia (continued). "It is estimated that 25-35% of adult patients with acute myeloid leukemia (AML) carry NPM1 mutations." (PMID 37794441, 2023). "C-terminal mutation of Nucleophosmin 1 (NPM1C+) was thought to be a primary driving event in acute myeloid leukemia (AML) that reprograms leukemic-associated transcription programs to transform hematopoietic stem and progenitor cells (HSPCs)." (PMID 37365294, 2023). "Mutated nucleophosmin 1 gene (NPM1) is the most common genetic alteration in adult acute myeloid leukaemia (AML), occurring in up to 30% of patients." (PMID 36922593, 2023). "The aim of this randomized clinical trial was to evaluate the impact of all-trans retinoic acid (ATRA) in combination with non-intensive chemotherapy in older unfit patients (> 60 years) with newly diagnosed NPM1-mutated acute myeloid leukemia." (PMID 37684299, 2023). "Acute myeloid leukemia (AML) with a nucleophosmin 1 (NPM1) mutation is a unique subtype of adult leukemia." (PMID 36675134, 2023). "Avrainvillamide, a nucleophosmin inhibitor, has shown potential inhibitory effects on the abnormal trafficking of mutated NPM1, which causes acute myeloid leukemia (AML)." (PMID 38002949, 2023). "Nucleophosmin 1(NPM1) mutated acute myeloid leukemia is recognized as distinct entity in the 2016 revision of the WHO classification." (PMID 36051025, 2022). "NPM1-mutated acute myeloid leukemia (AML) is one of the most common subtypes of AML in patients with a normal karyotype." (PMID 36612194, 2022). "Acute myeloid leukemia (AML) often occurs due to chromosomal abnormalities or mutations in the genes NPM1, CEPBA, RUNX1 and FLT3 and is characterized by an over-accumulation of abnormal cells called myeloblasts." (PMID 35159109, 2022). "In acute myeloid leukemia, molecular genetics abnormalities, particularly NPM1 and FLT3 mutations, have a recognized prognostic role in the ELN risk classification and guide treatment decisions, especially since the availability of FLT3-targeted drugs." (PMID 36230640, 2022). "The prognosis of acute myeloid leukemia depends on genetic aberrations, particularly NPM1 and FLT3-ITD mutations." (PMID 36230640, 2022). "Acute myeloid leukemia (AML) with NPM1 mutation and a normal karyotype comprises 30% of AML and is one of the most common subtypes." (PMID 36612194, 2022). "Mutations in the multifunctional ribonucleoprotein NPM1 are identified as drivers for acute myeloid leukemia in 30% of patients and frequently co-occur with pre-leukemic DNMT3A mutations." (PMID 33649320, 2021). "A discrepancy has been reported regarding the JAK2 V617F mutation in patients with essential thrombocythemia and polycythemia vera, and also regarding the type A mutation of NPM1 in acute myeloid leukemia (AML)." (PMID 33806359, 2021). "The incidence of NPM1 mutation (NPM1mut) accounts for approximately one-third of the cases of de novo acute myeloid leukemia (AML) and up to ~ 50% of normal karyotype (NK) AML." (PMID 34238278, 2021). "More specifically, mutations in NPM1 have been reported in approximately 50% of acute myeloid leukemia (AML) with a normal karyotype and represents a distinct subset of AML according to the World Health Organization classification." (PMID 34527579, 2021). "In particular, NPM1 is the most frequently mutated protein in acute myeloid leukaemia (AML), accounting for approximately one third of the patients." (PMID 34208390, 2021). "The most common single point mutation was found in NPM1 (W288Cfs*12 insertional frameshift mutation), which is found exclusively in acute myeloid leukemia (AML), and causes a frameshift mutation at the C-terminus." (PMID 32681070, 2020). "It was suggested that most NPM1 mutations in CMML patients likely indicated disease progression to acute myeloid leukemia." (PMID 33315966, 2020). "In this work, we dissect the functional role of the HOXB-AS3 lncRNA in patients with NPM1-mutated (NPM1mut) acute myeloid leukemia (AML)." (PMID 31767858, 2019).
acute myeloid leukemia (continued). "Mutations in the nucleophosmin 1 (NPM1) gene are considered founder mutations in the pathogenesis of acute myeloid leukemia (AML)." (PMID 31048683, 2019). "Acute myeloid leukemia with mutated NPM1 (NPM1mut) represents a distinct entity in the revised World Health Organization (WHO) classification, and the prognosis of patients carrying this mutation is generally considered favorable." (PMID 31569375, 2019). "In one patient with acute myeloid leukemia NPM1 mutation in CSF tumor cells was found and in one patient with lymphoma additional molecular genetic testing showed monoclonal rearrangement in immunoglobulin heavy chain gene in CSF lymphocytes." (PMID 31481919, 2019). "Mutations in the nucleophosmin 1 (NPM1) gene are the commonest molecular lesions occurring in ≥ 50% of cases with cytogenetically normal acute myeloid leukemia (CN-AML)." (PMID 31606046, 2019). "Acute myeloid leukemia (AML) with mutated NPM1 is a specific subtype of AML with a recurrent genetic abnormality and favourable outcome." (PMID 30564301, 2018). "For example, miR-10a has been found downregulated in CML but upregulated in NPM1-mutated acute myeloid leukemias (AML)." (PMID 30419846, 2018). "It is noteworthy that from the clinical point of view acute myeloid leukemia with mutated NPM1 is characterized by a better prognosis due to a higher remission rate after chemotherapy containing anthracyclines and cytarabine." (PMID 29855342, 2018). "Acute myeloid leukemia (AML) patients with NPM1 mutations demonstrate a superior response to standard chemotherapy treatment." (PMID 30089730, 2018). "Recently, by incorporating a potential modulator feature, NPM1 mutation, we proposed a prognostic predictor for acute myeloid leukemia based on the interaction strengths between several miRNAs and their modulated target genes." (PMID 28241741, 2017). "In this study, we evaluated the frequency of FMS-like tyrosine kinase 3 (FLT3-ITD and FLT3-TKD) and nucleophosmin (NPM1) mutations in Iranian patients with cytogenetically normal acute myeloid leukemia (CN-AML)." (PMID 28294102, 2017). "Mutations of the NPM1 gene are the most frequent genetic alterations in acute myeloid leukemia (AML) and result in the expression of a mutant protein with aberrant cytoplasmic localization, NPMc+." (PMID 27486814, 2016). "Mutated nucleophosmin 1 (NPM1) acts as a proto-oncogene and is present in ~30% of patients with acute myeloid leukemia (AML)." (PMID 27906185, 2016). "These aromatic residues constitute an atypical nucleolar localization signal (NoLS), and their mutation are responsible for the unfolding and the aberrant NPM1 localization typical in acute myeloid leukemia (AML) cases." (PMID 27553022, 2016). "Much interest in this protein has arisen in the past ten years, since the discovery of heterozygous mutations in the terminal exon of the NPM1 gene, which are the most frequent genetic alteration in acute myeloid leukemia." (PMID 27058426, 2016). "NPM1 in cancer is most strikingly highlighted in acute myeloid leukemia where approximately 30 % of patients will have a mutation or fusion event implicating NPM1." (PMID 27553022, 2016). "The NPM1 gene is mutated or rearranged in a number of hematological disorders, and it was considered as the most frequently mutated gene in acute myeloid leukemia." (PMID 25779011, 2015). "Mutations of the NPM1 gene resulting in the expression of a cytoplasmic mutant protein, NPMc+, are the most frequent genetic abnormalities found in acute myeloid leukemia." (PMID 25779011, 2015). "NPM1 is mutated or aberrantly localized in about one-third of patients with acute myeloid leukaemia (AML)." (PMID 25663821, 2014).